MET (MET proto-oncogene, receptor tyrosine kinase)
Diseases named in the same sentence as MET in open-access papers (continued):
Sharing a sentence is not in itself a finding about the gene and the disease.
papillary thyroid carcinoma (27 papers, 2004 to 2025). "TFG-MET (MET proto-oncogene receptor tyrosine-kinase) translocation was reported in a follicular variant of the papillary thyroid carcinoma." (PMID 31349573, 2019). "Given the critical role of loss of thyroid differentiation in papillary thyroid carcinoma (PTC) progression, we utilized TIMER 2.0 to systematically analyze the association between MET expression and 15 key thyroid differentiation genes." (PMID 41233563, 2025). "Studies have shown that LAMB3 leads to tumor invasion via Akt activation induced by the HGF/c-MET axis in papillary thyroid cancer." (PMID 31485443, 2019). "MET p.T992I, found in 6 of our patients, has also been reported in familial colorectal and differentiated thyroid cancers, both PHTS component malignancies, although the transforming capacity of this variant has been debated." (PMID 29684080, 2018). "Taken together all these observations suggest that over-expression of MET gene has a central role in the tumorigenesis of papillary carcinoma of the thyroid." (PMID 28548071, 2014). "In our first case, cMet was found mutated and the second case has a papillary carcinoma which is known to commonly have MET gene alterations, although no mutation in this gene was found in the tumor of this patient." (PMID 30474572, 2018). "Thus, overexpression of MET protein might represent an immunohistochemical marker of papillary carcinoma, potentially helpful in problematic cases." (PMID 26062519, 2016). "Genes less commonly rearranged in papillary carcinoma with BRAF V600E-like signature include BRAF, MET and ROS1 (e.g., CUL1-BRAF, MKRN1-BRAF, SND1-BRAF, TTYH3-BRAF CCDC30-ROS1 EML4-MET, and TFG-MET)." (PMID 41175860, 2025). "Via bioinformatics analysis and experimental validation, MET and ICAM1 were found to be upregulated in lymph node metastasis from papillary thyroid carcinoma." (PMID 37274228, 2023). "Via bioinformatics analysis and experimental validation, the expressions of MET and ICAM1 were found to be upregulated in patients with lymph node metastasis from papillary thyroid carcinoma." (PMID 37274228, 2023).
mesothelioma (26 papers, 2008 to 2024). A usually malignant and aggressive neoplasm of the mesothelium which is often associated with exposure to asbestos. "Although, preclinical investigations indicate that the HGF-MET axis may play an important role in mesothelioma-genesis and that MET can be upregulated in MM cell lines, MET-mutations are extremely uncommon in MM tissue specimens or MM cell lines." (PMID 34884673, 2021). "c-MET based immunotherapy has also been tested in pre-clinical mesothelioma models on the basis of MET chimeric antigen receptor T-cell (CAR-T) immunotherapy." (PMID 35081970, 2022). "Using several mesothelioma cell lines, our group showed that the small molecule MET inhibitor SU11274 suppresses cell proliferation." (PMID 25221930, 2014). "Our studies using PamGene microarray analysis revealed that ARQ 197 indeed targets MET in mesothelioma cells; however it also inhibited RON." (PMID 25221930, 2014). "These in silico analyses demonstrate that the MST1R and TYRO3 receptors are significantly overexpressed in mesothelioma, confirming previous data regarding MET and AXL, and suggesting that all four receptors may be candidate targets for therapy in MPM." (PMID 30863365, 2019). "Immunostaining of ALK, MET and mTOR on tissue microarrays was interpretable in 101 mesotheliomas." (PMID 29755689, 2018). "IC50 of Mesothelioma cell lines with MET and PI3K/mTOR inhibitors." (PMID 25221930, 2014). "Our results imply that MET overexpression occurs in a substantial fraction of predominantly epithelioid MMs, but correlates poorly with MET-amplification status, and may impact the likelihood of response to mesothelioma standard chemotherapy." (PMID 34884673, 2021). "The HGF-receptor (c-MET) and the PDGF receptors α and β, are detected in the majority of mesothelioma specimens by IHC." (PMID 31867277, 2019). "To assess the frequency of co-activation in primary mesotheliomas, we examined the co-expression of mTOR and ALK, ROS1, and MET at both mRNA and protein levels in tumor samples by qRT-PCR and IHC, respectively." (PMID 29755689, 2018). "Various studies have reported on the expression and activation of RTKs in mesothelioma, including EGFR, MET, IGFR, FGFR1, and VEGFR." (PMID 29755689, 2018). "Recently, it was shown that the combination of rapamycin or PI3K/mTOR inhibitors and one specific RTK inhibitor (EGFR, MET or IGF1R inhibitor) suppressed adverse AKT activation and hampered mesothelioma cell growth in vitro and in MPM xenografts." (PMID 29755689, 2018). "Here we determined the combinatorial therapeutic efficacy of a new generation small molecule inhibitor of MET, ARQ 197, and dual PI3K/mTOR inhibitors NVP-BEZ235 and GDC-0980 in mesothelioma cell and mouse xenograft models." (PMID 25221930, 2014). "While it is well established that the Hepatocyte Growth Factor Receptor (MET) is frequently overexpressed and activated in mesothelioma, to our knowledge this is the first indication that it's less well-studied family member, MST1R (RON) is also frequently activated in MPM." (PMID 30863365, 2019). "Specific inhibition of VEGFR, FGFR1, MET and/or EGFR suppressed mesothelioma cell growth in vitro." (PMID 29755689, 2018). "Furthermore, MeT-5A may not have been a robust control cell line for mesothelioma." (PMID 37190292, 2023).
neuroblastoma (23 papers, 2009 to 2025). Neuroblastoma (NB) is the most common solid, extracranial childhood tumor. "Vascular endothelial growth factor (VEGF) and hepatocyte growth factor (HGF)/c-MET signalling are implicated in neuroblastoma progression." (PMID 40359728, 2025). "The MET/multikinase inhibitor cabozantinib blocked neuroblastoma cell proliferation and migration and efficiently reduced in vivo neuroblastoma tumor growth and metastases in orthotopic xenograft mouse models." (PMID 34716856, 2022). "Although they did not observe any effects on in vitro proliferation, the authors reported a very clear role for HGF/MET signaling in migration/invasion of neuroblastoma cells, both in vitro and in vivo." (PMID 34716856, 2022). "It was also reported that the knockdown of beta-catenin can restore the response to crizotinib in neuroblastoma, which may support the observed positive effect of beta-catenin deficiency in our cohort and imply a strategy of combining inhibitors against beta-catenin and MET/ALK." (PMID 35628499, 2022). "The same group also showed that NTRK2 activation preceded and mediated HGF/MET upregulation in neuroblastoma cell lines." (PMID 34716856, 2022). "Analyses for MET amplification, alternatively spliced isoforms, or protein over-expression in a small cohort of neuroblastoma tumor samples (54 samples) suggested a low prevalence of such alterations." (PMID 34716856, 2022). "The neuroblastoma SK-N-SH cells with HGF overexpression which activates MET signalling are sensitive to MET inhibitors." (PMID 31137515, 2019). "The HGF overexpression in SK-N-SH cells would activate MET signalling and be responsible for the cancer cell growth, which is accordant with the clinical status of neuroblastoma cancer patients." (PMID 31137515, 2019). "Several angiogenic signalling pathways have been implicated in neuroblastoma progression, including vascular endothelial growth factor (VEGF), the most potent angiogenic growth factor, and the hepatocyte growth factor (HGF) receptor MET." (PMID 40359728, 2025). "However, the development of novel small molecule inhibitors targeting c-MET activity has prompted to a re-evaluation of HGF/MET signaling in neuroblastoma and other cancer paradigms." (PMID 34716856, 2022). "Furthermore, they also found that sublethal irradiation led to upregulation of HGF and MET in neuroblastoma cell lines, resulting in enhanced migratory behavior." (PMID 34716856, 2022). "The highly selective MET inhibitor PHA665752 was shown to significantly reduce in vitro migration and proliferation on two neuroblastoma cell lines in a dose-dependent manner." (PMID 34716856, 2022). "Regarding neuroblastoma, initial studies demonstrated a role for HGF/MET signaling in the migration and/or differentiation of neural crest cell-derived structures." (PMID 34716856, 2022). "Once more, the fact that some of such RTKs have previously been described as important players in neuroblastoma tumor biology (e.g., ALK, KIT, MET, and RET) again validates this approach." (PMID 34716856, 2022). "The MET inhibitor EMD1214063 was also shown to efficiently reduce in vitro viability and inhibit in vivo neuroblastoma tumor growth in orthotopic xenograft mouse models." (PMID 34716856, 2022). "Cabozantinib, a multi-targeting inhibitor of MET, VEGFR2, AXL, and RET, can overcome HGF/MET signaling-mediated resistance to pan-VEGFR inhibition in neuroblastoma mouse models." (PMID 29560266, 2018). "Several RTKs, including ALK, KIT, MET, NTRK2, and RET, play a major role in neuroblastoma pathogenesis, and their activation could be responsible for adaptive resistance to trametinib and ganitumab in neuroblastoma." (PMID 39001383, 2024). "All neuroblastoma cell lines expressed ALK, with strong expression in LAN-5 cells and amplification in NB-1 cells, whereas the other target of crizotinib, c-MET, was not expressed." (PMID 29515255, 2018).
neuroblastoma (continued). "Of note, though the average cell death rate in non-neuroblastoma and non-ALK expressing cell lines (RD and VH7) was below 10% for all treatment conditions, crizotinib treatment increased the amount of dead cells, presumably by interacting with c-MET." (PMID 29515255, 2018). "However, both non-neuroblastoma control lines (RD and VH7) expressed c-MET while ALK expression was not detectable." (PMID 29515255, 2018).
rhabdomyosarcoma (23 papers, 2011 to 2024). A rare aggressive malignant mesenchymal neoplasm arising from skeletal muscle. "Our group has previously shown that MET downregulation causes a decrease in the size of tumors derived from rhabdomyosarcoma (RMS) cells transplanted into a NOD-SCID mouse model." (PMID 25888626, 2015). "The aim of this study was to investigate which of the molecular mechanisms associated with constitutive activation of MET signaling are responsible for rhabdomyosarcoma development and malignancy." (PMID 26384300, 2015). "To conclude, our results suggest that activation of MET signaling may cause defects in myogenic differentiation leading to rhabdomyosarcoma development and progression." (PMID 26384300, 2015). "By using a rhabdomyosarcoma cell line that conditionally expresses miR-206, we verified that miR-206 induction promoted MET mRNA downregulation, but spared circMET." (PMID 37170152, 2023). "For instance, c-MET was identified as a direct target of PAX3-FOXO1 in alveolar rhabdomyosarcoma and EWS-ATF1 in clear cell sarcoma." (PMID 28511645, 2017). "Our previous study and current analysis of new rhabdomyosarcoma tumor samples demonstrated that expression of MET mRNA is lower in embryonal (ERMS) than in alveolar (ARMS) subtype, which is usually associated with more malignant phenotype." (PMID 26384300, 2015). "The salient finding of the present study is that constitutive activation of MET signaling by expression of TPR-MET oncogene induces rhabdomyosarcoma development by blocking myogenic differentiation and enhancing proliferation, migration and angiogenesis." (PMID 26384300, 2015). "We identified MET as a proposed target of miR-206 and this prediction is supported by Yan and colleagues, who showed that miR-206 targets MET and inhibits rhabdomyosarcoma development." (PMID 24977165, 2014). "Despite MET has recently been identified as a target of miR-206 in rhabdomyosarcoma cells." (PMID 27014910, 2016). "All lines expressed the RON protein, as did the rhabdomyosarcoma cell lines, which were included into this study to address potential interaction of RON with its RTK family member MET." (PMID 32272784, 2020). "To determine if activation of MET signaling pathways may be responsible for activation of oncogenic and metastatic pathways in rhabdomyosarcoma development, we transduced SMS-CTR cells using lentiviral vectors harboring TPR-MET oncogene." (PMID 26384300, 2015).
autism (22 papers, 2009 to 2025). Persistent deficits in social interaction and communication and interaction as well as a markedly restricted repertoire of activity and interest as well as repetitive patterns of behavior. "Our laboratory discovered that the gene encoding the receptor tyrosine kinase, MET, contributes to autism risk." (PMID 26523156, 2015). "Several evidences show a genetic predisposition to autism that involves a reduced expression of gene coding for Hepatocyte growth factor receptor (HGFR), also known as mesenchymal-epithelial transition factor (MET)." (PMID 24605324, 2014). "For example the MET gene, one of the most studies genetic regions in autism, has a relative risk of 2.27." (PMID 22928105, 2012). "We therefore started our studies of the genetics of autism in China with a replication study focusing on MET variants." (PMID 22110649, 2011). "Interestingly, human Cav1 is located at 7q31.1, part of autism-linked locus 9 (Auts9), immediately upstream of MET, which shows direct pretranscription start-site mutations associated with ASD." (PMID 29379878, 2018). "Interestingly, polymorphisms in the MET gene appear to confer an increased susceptibility to autism and this gene is included in the chromosome 7q31 that has been linked to autism susceptibility." (PMID 28751869, 2017). "One of the most interesting genetic findings in ASD is the association of autism with the MET receptor tyrosine kinase gene located on chromosome 7q31 as MET signaling participates in gastrointestinal repair, immune function, neocortical, and cerebellar growth." (PMID 22928105, 2012). "This could suggest the presence of genetic heterogeneity, with different variants of the MET gene contributing to autism aetiology in different populations." (PMID 22110649, 2011). "Interestingly, polymorphisms in the MET promoter have recently been described to confer an increased susceptibility to autism and this gene is included in one of the genomic sequences linked to autism susceptibility (7q31)." (PMID 21876820, 2011). "Increased risk for autism, due to a functional polymorphism in the MET gene, and lower levels of unbound HGF, may impart, particularly in individuals with severe GI disease, shared etiology of a parallel, although independent, disruption of brain and peripheral organ development and function." (PMID 20029653, 2009). "Although hypothetical, deficiency in either HGF or c-MET could initiate and promote a sustained immune response consistent with chronic features of autism pathophysiology, and could therefore be an important contributor to the autism phenotype." (PMID 20029653, 2009). "In particular a 2-fold decrease in MET promoter activity and altered binding of specific transcription factor was observed in 204 autism families." (PMID 24605324, 2014). "This includes dose-sensitive genes such as MET, which is a candidate gene in autism." (PMID 38539661, 2024). "A more comprehensive evaluation of the oncogene and tumor suppressor variants found in this study is ongoing; nevertheless, the variations discovered in two oncogenes, PIK3CA and MET, implicate specific mechanisms that could link autism and neoplasm." (PMID 26934580, 2016). "Association studies investigating WNT2, DISC1, MET, DOCK4 or AHI1 also provide evidence that the canonical Wnt pathway might be affected in autism." (PMID 23083465, 2012). "The MET gene located in the region was considered a good candidate both because of the biological importance of the MET/HGF signalling pathway in autism aetiology and also because of the successful association of MET variants with autism in previous studies in European and Japanese populations." (PMID 22110649, 2011). "Phenotypic characteristics caused by impaired MET/HGF signalling such as modified neuronal migration and disrupted neuronal growth in the cortex, as well as a decreased proliferation of granule cells causing a parallel reduction in the size of the cerebellum, have been seen in the autism patients." (PMID 22110649, 2011).
autism (continued). "Nonetheless, levels of c-MET expression were not significantly altered in a recent study analyzing the PFC of autism patients." (PMID 31949148, 2020).